DEFB103A (defensin beta 103A)
Description:
Exhibits antimicrobial activity against Gram-positive bacteria S.aureus and S.pyogenes, Gram-negative bacteria P.aeruginosa and E.coli and the yeast C.albicans. Kills multiresistant S.aureus and vancomycin-resistant E.faecium. No significant hemolytic activity was observed.
Synonyms: BD-3; DEFB-3; HBD3; hBD-3; DEFB103; DEFB3; HBP-3; HBP3
Tractability: Antibody: its Gene Ontology location is reachable by antibodies, with high confidence; UniProt places it where antibodies can reach, with medium confidence; UniProt predicts a signal peptide or a membrane-spanning region.
Gene: Protein-coding gene on chromosome 8 (7,881,392 to 7,882,663, forward strand). Ensembl gene ENSG00000176797.
Subcellular location: Secreted
Pathways (Reactome):
Immune System: Beta defensins; Defensins
Gene Ontology:
Molecular function: protein binding; CCR6 chemokine receptor binding; chemoattractant activity
Biological process: antibacterial innate immune response; defense response to bacterium; defense response to Gram-negative bacterium; defense response to Gram-positive bacterium; killing of cells of another organism; cell chemotaxis; defense response; positive chemotaxis
Cellular component: extracellular region; Golgi lumen
Homologues: Orthologues: chimpanzee DEFB103A (99% identical), dog CBD103 (78% identical), mouse Defb14 (69% identical), rat Defb14 (67% identical). Paralogues in human: DEFB103B (100% identical).
Diseases named in the same sentence as DEFB103A in open-access papers:
DEFB103A is named in the same sentence as 5 diseases in open-access papers, as found by Europe PMC text mining. Sharing a sentence is not in itself a finding about the gene and the disease. The quoted sentences say what the papers report.
psoriasis (3 papers, 2020 to 2025). An autoimmune condition characterized by red, well-delineated plaques with silvery scales that are usually on the extensor surfaces and scalp. "The co-expression shifts of HKGs with psoriasis-associated genes (e.g., DEFB103A/B, S100A7A, IL36RN) further demonstrate their regulatory influence." (PMID 40959079, 2025). "Our data confirmed several proteins already known to be associated with psoriasis, including S100A7, S100A9, beta-defensin 3(DEFB103A), Elafin (PI3), serine protease inhibitors B3, and B4." (PMID 32849499, 2020). "In summary, the study identified a series of characteristic genes (DEFB103A, IFI16, OAS3, OASL, SAMD9, STAT1, etc.)that are highly related to the occurrence, treatment of psoriasis." (PMID 40560938, 2025).
squamous cell carcinoma (1 paper, 2016). A carcinoma arising from squamous epithelial cells. "We have reported that proliferating oral mucosal basal layer cells as well as tumor cells in carcinoma in situ lesions and at the invasive front of squamous cell carcinoma produce hBD3, which is encoded by the DEFB103A gene, with little-to-no expression of hBD-1 and -2." (PMID 27034006, 2016).
viral infection (1 paper, 2024). "Several of the upregulated genes indicated a cellular response to viral infection (CXCL11, CCL8, DEFB103A, IFI6, ACOD1, and DEFB4A)." (PMID 38755665, 2024).
DEFB103A also shares sentences with these, for which no sentence is quoted: carcinoma in situ (1 paper); tumor (1).